DUSP1 (dual specificity phosphatase 1)
Diseases named in the same sentence as DUSP1 in open-access papers (continued):
Sharing a sentence is not in itself a finding about the gene and the disease.
melanoma (17 papers, 2011 to 2025). A malignant, usually aggressive tumor composed of atypical, neoplastic melanocytes. "DUSP1 was consistently downregulated in BRAFi-R melanomas, which was reversed by corin treatment and associated with inhibition of p38 MAPK activity and resensitization to BRAFi therapies." (PMID 38300709, 2024). "In melanoma patients, the low expression of DUSP-1 has been associated with worsened overall survival, probably mediated by the reduced dephosphorylation rate of several MAPKs and consequent increase in the proliferation rate." (PMID 37160873, 2023). "Query of TCGA melanoma dataset showed that high DUSP1 mRNA expression is associated with better overall survival." (PMID 35999349, 2022). "Importantly, in human cancers such as prostate, melanoma, pancreatic, glial, ovarian, testicular, salivary gland squamous cell carcinomas (SG-SCCs), and gastric cancers, DUSP1 expression is associated with cancer cell proliferation or suppression." (PMID 41158869, 2025). "In addition, p38 MAPK activity was shown to be inhibited in all NRAS-mutant melanoma cell lines following corin treatment, with associated increases in DUSP1 and DUSP5 expression." (PMID 38300709, 2024). "Remarkably, we found significantly reduced expression of several DUSPs, including DUSP1, in 451Lu-R and 1205Lu-R melanoma cell lines compared with their BRAFi-S counterparts, suggesting a potential role for DUSP proteins in regulating BRAFi resistance." (PMID 38300709, 2024). "We therefore explored the role of DUSP1/p38 MAPK in NRAS-mutant melanomas and evaluated the effect of corin in dose-response assays." (PMID 38300709, 2024). "DUSP1 is a direct target of the CoREST complex and promotes a response to BRAFi therapy in BRAFi-R melanoma." (PMID 38300709, 2024). "To further explore the functional significance of DUSP1 expression in BRAFi-R melanoma, we induced constitutive expression of DUSP1 in BRAFi-R melanoma cells." (PMID 38300709, 2024). "Treatment of BRAFi-R melanoma cells with corin alone or combination treatment with corin plus PLX4032 resulted in up to 75-fold increases in DUSP1 expression compared with treatment with vehicle." (PMID 38300709, 2024). "Additional studies are warranted on the role of DUSPs, in general and DUSP1 in particular, in melanoma drug resistance and their potential as targets for treatment of melanoma." (PMID 35999349, 2022). "In summary our data implicate DUSPs, specifically DUSP1, as mechanistic link between melanoma plasticity, tendency to differentiate along neural linages and emergence of MAPKi resistance phenotype." (PMID 35999349, 2022). "In melanoma cells with acquired MAPKi-resistance, BRAFi and MEKi downregulate DUSP1, and knockdown or inhibition of DUSP1 alone can overcome both intrinsic and acquired MAPKi-resistance." (PMID 35999349, 2022). "Several members of the DUSP family genes, specifically DUSP1, -3, -8 and -9, are expressed in primary and metastatic melanoma cell lines and pre-and post BRAFi treated melanoma cells." (PMID 35999349, 2022). "In this study, we found that treatment of melanoma cells with BCI, a DUSP1/DUSP6 inhibitor at a concentration close to IC50 for selective inhibition of DUSP1, caused upregulation of nestin and immature MAP2 in MAPKi-sensitive cells." (PMID 35999349, 2022). "In this study, CYR61, DUSP1, and RNASE4 were identified as potential genes of interest for future molecular studies in melanoma, which would improve our understanding of its causes and underlying molecular events." (PMID 30925905, 2019). "Preclinical studies indicate that therapeutically targeting DUSP1 may improve outcomes in several cancers, including pancreatic, ovarian, and melanoma." (PMID 41158869, 2025). "As DUSP1 effects on p38 MAPK appeared to be a critical mediator of corin effects on melanoma resistance to BRAFi therapy, we sought to determine whether inhibition of the p38 MAPK target of DUSP1 would phenocopy the effects of corin on BRAFi-R melanoma cells." (PMID 38300709, 2024).
melanoma (continued). "In this study, we demonstrate that the CoREST repressor complex plays a critical role in promoting cellular plasticity and phenotype switching in melanoma as well as in resistance to targeted BRAFi therapies through repression of the dual-specificity phosphatase DUSP1." (PMID 38300709, 2024). "1205Lu-R cells overexpressing DUSP1 showed significant growth inhibition following PLX4032 treatment compared with vector control, suggesting that DUSP1 expression could resensitize BRAFi-R melanoma cells to PLX4032." (PMID 38300709, 2024). "Notably, DUSP1 expression was significantly decreased in malignant melanoma compared with both benign nevi and normal skin, and decreased DUSP1 protein expression was noted in malignant melanoma tissues versus benign nevi by immunohistochemistry." (PMID 38300709, 2024). "Of note, increased DUSP1 expression alone was associated with improved overall survival in patients with melanoma, as previously reported; however, those data did not achieve statistical significance in the cohort we evaluated." (PMID 38300709, 2024). "Thus, intrinsically MAPKi-resistant MRA5 cells appear to be more sensitive DUSP1 inhibition than melanoma cells with acquired resistance." (PMID 35999349, 2022). "To understand the role of DUSPs in melanoma cell survival, we used siRNA-mediated knockdown (KD) of DUSP1 or DUSP8, employing MISSION® esiRNAs (Millipore Sigma), which are endoribonuclease prepared heterogeneous pools of siRNA that all target the same mRNA sequence." (PMID 35999349, 2022). "Our analysis of available melanoma gene expression studies of melanoma tumors and patient-derived xenografts pre- and post-BRAFi (resistant) showed that several DUSPs, including DUSP1, are downregulated in the resistant tumors (both in bulk and single cell RNAseq datasets)." (PMID 35999349, 2022). "In addition, the DUSP1 promoter was found to possess a significant number of AP-1– and EMT-associated transcription factor binding sites that were notably associated with corin effects on BRAFi-R melanoma cells." (PMID 38300709, 2024). "In contrast, DUSP1 knockdown in human melanoma cells led to loss of PLX4032 sensitivity in BRAFi-S melanoma cells, with associated activation of p38 MAPK in 1205Lu cells, further supporting a critical role for DUSP1 in mediating melanoma resistance to BRAFi treatment." (PMID 38300709, 2024). "In order to explore the relationship between DUSP1 expression and melanomagenesis in patients, we mined publicly available gene expression data sets for normal skin, benign nevi, and patients’ primary melanoma tissues from The Cancer Genome Atlas (TCGA) repository." (PMID 38300709, 2024). "Interestingly, TNF-α signalling via the NF-κB pathway was significantly downregulated with a reduction ranging from 7- to 40-fold in expression of some of its prooncogenic target genes (e.g., JUNB, FOS, DUSP1) and melanoma-related genes (e.g., EGR3, NR4A3, CCN1)." (PMID 34497073, 2021). "In primary and metastatic melanoma, DUSP1 knockdown and pharmacologic DUSP1 inhibition decreased MAPK-inhibitor resistance and sensitized melanoma cells to BRAF and MEK inhibitors." (PMID 41158869, 2025). "We validated the expression of DUSP1, SLAMF7 and EVI2B in human melanoma cell UACC62 and UACC257 after 8 Gy gamma-ray." (PMID 39687627, 2024). "TCGA data were further analyzed to explore the relationship between DUSP1 and RCOR1 expression in 412 melanoma specimens from patients." (PMID 38300709, 2024). "In melanoma, TFEB has also been reported to be able to affect cell metabolism and proliferation by regulating the DUSP‐1/ERK1/2 pathway." (PMID 38938061, 2024). "Notably, our experiments showed the complete rescue of ERK1/2 phosphorylation after DUSP-1 activity inhibition but only a partial recovery of Cyclin D1 expression, suggesting that other unknown mechanisms might be involved in Tfeb silencing of melanoma cells." (PMID 37160873, 2023).
melanoma (continued). "TFEB is a repressor of dual-specific phosphatase-1 (DUSP-1), which is a key negative regulator of MAPK in mammalian cells, including melanoma cells." (PMID 37160873, 2023). "For the malignant melanoma cells, PMEL, IFITM1, HSPA1A, DUSP1, FOS and TMSB4X are the shared driver genes across three subtypes in S4 File." (PMID 38096269, 2023). "A further analysis of MAPK regulatory genes showed that mRNAs for several DUSPs-DUSP1 DUSP5, DUSP8, DUSP10 and DUSP14-were upregulated in intrinsically MAPKi-resistant melanoma cell line." (PMID 35999349, 2022). "We observed that BCI-215, a DUSP1/6 inhibitor in B16F10 cells, reduced the melanin content efficiently in B16F10 melanoma cells." (PMID 36080217, 2022). "The melanoma immunotherapy dataset PRJEB23709(n=91), GSE100797(n=25), GSE78220(n=28), GSE91061(n=109), Nathanson_2017(n=24), phs000452(n=153) were included to analyze the influence of DUSP1, CXCL13, SLAMF7 and EVI2B in immunotherapy response." (PMID 39687627, 2024). "Furthermore, targeting of the CoREST complex with the small-molecule inhibitor corin led to increased expression of DUSP1, inhibition of p38 MAPK activity, and resensitization of BRAF-resistant melanomas to BRAFi therapy." (PMID 38300709, 2024). "As increased DUSP1 and DUSP5 expression occurred with corin treatment of BRAFi-R melanoma cells, we sought to establish baseline levels of DUSPs in BRAF-sensitive and BRAF-resistant melanoma cell lines." (PMID 38300709, 2024). "Interestingly, DUSP1, -8 and -9 appear to be downregulated and DUSP3 is upregulated in LNM WM165-1 compared to primary melanoma and other LNM derived cells." (PMID 35999349, 2022). "Next, we investigated the effect of DUSP1 and DUSP8 KD on MAPKi sensitivity of melanoma cells." (PMID 35999349, 2022). "In this study, we found that DUSP-1, -3, -8, and -9 expression is downregulated in advanced metastatic, but not early lymph node metastatic, melanoma cells." (PMID 35999349, 2022). "Notably, Singh and colleagues recently reported that melanoma cells are reliant on DUSP1 and DUSP8 expression for proliferation and that DUSP1 protein expression is reduced in MAPKi-sensitive and -resistant melanoma cells treated with BRAFi, consistent with the data reported here." (PMID 38300709, 2024). "Furthermore, we noticed an increase in DUSP1 (Dual Specificity Phosphatase 1), STK3 (Serine/Threonine Kinase 3), ACTA2 (Actin, alpha 2, smooth muscle, aorta) and IL1A (Interleukin 1α) gene expression levels; however, the role of these genes in melanoma repopulation remains to be addressed." (PMID 31597943, 2019).
gastric cancer (16 papers, 2016 to 2026). A primary or metastatic malignant neoplasm involving the stomach. "The hub gene-based risk model (DUSP1/TNF/NOX4/LONP1) shows promise as an overall survival predictor in gastric cancer." (PMID 38758860, 2024). "Higher expression of DUSP1 has been linked to better overall survival, indicating its potential as a prognostic marker in gastric cancer." (PMID 37999824, 2023). "DUSP1 (Dual specificity protein phosphatase 1) is an oncogene that is associated with cancer progression in gastric cancer as well as a negative regulator of the mitogen-activated protein kinase (MAPK) signaling pathway, has anti-inflammatory properties." (PMID 30925905, 2019). "In most cancers, such as prostate, ovarian, colon, and gastric cancer, progressive loss of DUSP1 is detected with histological grade increasing." (PMID 27227569, 2016). "In prostate, ovarian, colon and gastric cancers, progressive loss/reduction of DUSP1 is detected with increasing histological grade, which indicates DUSP1 may act a tumor suppressor in those settings." (PMID 28129656, 2017). "DUSP1 stood out as a key player in gastric cancer progression, with higher expression in tumor tissues and a significant role in cell proliferation, apoptosis, and drug resistance." (PMID 40489463, 2025). "In this study, we analyzed the expression of DUSP1 in gastric cancer and found that it was significantly higher in tumor tissues compared to normal tissues." (PMID 40489463, 2025). "Together, among the many key mitophagy-related genes, the DUSP1 was as a key protein leading to progression of gastric cancer." (PMID 40489463, 2025). "DUSP1 can exert tumor-suppressive effects in gastric cancer by negatively regulating MAPK signaling pathways that control cell proliferation, survival, and invasion." (PMID 37999824, 2023). "According to reports on cell cycle regulation, an increase in DUSP1 expression in gastric cancer leads to a cell cycle arrest in the G1 phase, and it has been reported that DUSP1 expression in cumulus cells is reduced in the G0/G1 phase and increased in the S phase." (PMID 40415961, 2025). "DUSP1 is prognostic for patients with gastric cancer and important in immune cell regulation." (PMID 40867253, 2025). "Additionally, knockdown of DUSP1 significantly inhibited the proliferation and migration of gastric cancer cells." (PMID 40489463, 2025). "Additionally, we only investigated the role of the core gene DUSP1 in gastric cancer, and the functional experiments of other genes in the model need further validation to explore the role and mechanisms of autophagy-related genes in gastric cancer." (PMID 40489463, 2025). "DUSP1 is significantly overexpressed in apatinib‐resistant patients with gastric cancer, and downregulating DUSP1 may be a potential measure to attenuate apatinib resistance in gastric cancer." (PMID 38647235, 2024). "Notably, DUSP1 expression was significantly elevated in various cell types within gastric cancer tissues, suggesting that DUSP1 may play a crucial role in the progression of gastric cancer." (PMID 40489463, 2025). "An immunohistochemical (IHC) investigation assessed the expression levels of hub genes (SDC2, RGS4, SERPINE1, DUSP1, and CAV1) in gastric cancer." (PMID 39871942, 2024). "DUSP1 is highly expressed in human paracancerous tissues and overexpression of MAPK pathway induces apatinib resistance in gastric cancer." (PMID 36479092, 2022).
atherosclerosis (14 papers, 2012 to 2024). A disease characterized by the build-up of fatty material and calcium deposition in the arterial wall resulting in partial or complete occlusion of the arterial lumen. "DUSP-1 and DUSP-6 expression levels are elevated in a number of cardiovascular diseases and DUSP-1 deficient mice are protected from atherosclerosis development." (PMID 34493753, 2021). "Specifically, DUSP1 was the second-highest DEG in monocytes isolated from patients with atherosclerosis compared with those from healthy volunteers." (PMID 39718832, 2024). "In the KEGG analysis, some signaling pathways were identified, such as fluid shear stress and atherosclerosis (involved DUSP1)." (PMID 37699956, 2023). "Currently, the mechanism by which DUSP1 regulates atherosclerosis progression is still controversial." (PMID 35087573, 2021). "Interestingly, DUSP1 is downregulated in vascular endothelium under shear stress and acts as a protective factor during the early inflammatory phase of atherosclerosis." (PMID 39086489, 2024). "In atherosclerosis, DUSP1 plays a promoter and suppressor role." (PMID 37699956, 2023). "Additionally, DUSP1 was also been reported to play promoter and suppressor roles in atherosclerosis." (PMID 35746962, 2022). "Several of the differentially regulated genes are involved in vascular pathophysiology; for example: DNAJB6 and DUSP1 (atherosclerosis), NAMPT (vascular inflammation), FCAR (myocardial infarction), IL8 (vascular remodelling), FFAR2 (lipid metabolism) and SOD2 (idiopathic cardiomyopathy (IDC))." (PMID 22409835, 2012). "In addition, DUSP1 was involved in fluid shear stress and atherosclerosis." (PMID 37699956, 2023). "In addition, DUSP1 is involved in the signaling pathway of fluid shear stress and atherosclerosis." (PMID 37699956, 2023). "It is speculated that DUSP1 may be involved in the process of atherosclerosis in IS." (PMID 37699956, 2023). "Similarly, a previous study of the monocyte transcriptome from subjects with atherosclerosis had shown that up-regulation of FOS and DUSP1 was a reliable biomarker of disease severity (especially of the inflammatory state)." (PMID 23185405, 2012).